LHX9 (LIM homeobox 9)
Description:
Involved in gonadal development.
Tractability: No criterion of Open Targets' tractability assessment is met for any kind of drug.
Gene: Protein-coding gene on chromosome 1 (197,911,902 to 197,935,478, forward strand). Ensembl gene ENSG00000143355.
Subcellular location: Nucleus
Subcellular location (Human Protein Atlas): Nucleoplasm
Pathways (Reactome):
Developmental Biology: Regulation of expression of SLITs and ROBOs
Gene Ontology:
Molecular function: protein binding; sequence-specific double-stranded DNA binding; DNA-binding transcription factor activity, RNA polymerase II-specific; RNA polymerase II transcription regulatory region sequence-specific DNA binding; DNA binding; sequence-specific DNA binding
Biological process: dorsal spinal cord interneuron anterior axon guidance; negative regulation of DNA-templated transcription; neuron differentiation; regulation of transcription by RNA polymerase II; regulation of DNA-templated transcription
Cellular component: chromatin; nucleus
Genetic constraint (gnomAD): Loss-of-function variants: 9 observed, 38.24 expected, observed/expected ratio (o/e) 0.24, 90% interval 0.14 to 0.41. The upper end of that interval is the gene's LOEUF score, 0.41, which puts it in group 1 of 6, group 1 being the genes least tolerant of losing a copy. Missense variants: 464 observed, 542.54 expected, observed/expected ratio (o/e) 0.86, 90% interval 0.79 to 0.92. Synonymous variants: 211 observed, 219.97 expected, observed/expected ratio (o/e) 0.96, 90% interval 0.86 to 1.08.
Homologues: Orthologues: chimpanzee LHX9 (100% identical), dog LHX9 (100% identical), macaque LHX9 (100% identical), guinea pig LHX9 (99% identical), rat Lhx9 (99% identical), mouse Lhx9 (98% identical), rabbit LHX9 (96% identical), pig LHX9 (94% identical), zebrafish lhx9 (90% identical), tropical clawed frog lhx9 (85% identical). Paralogues in human: LHX2 (71% identical), ZFHX3 (29% identical), LHX6 (28% identical), ZFHX4 (28% identical), LHX8 (27% identical), LMX1B (25% identical), LMX1A (25% identical), LHX3 (24% identical), LHX5 (23% identical), LHX1 (23% identical), LHX4 (22% identical), ZFHX2 (22% identical), and 8 more.